MICA (MHC class I polypeptide-related sequence A)
Diseases named in the same sentence as MICA in open-access papers (continued):
Sharing a sentence is not in itself a finding about the gene and the disease.
cancer (continued). "Our pediatric cancer patients had lower plasma concentrations of soluble MICA and ULBP2 than their healthy age matched counterparts excluding this as a possible explanation for the reduced K562 killing we observed." (PMID 39310750, 2024). "MICA is frequently overexpressed on the surface of cancer cells of epithelial and hematopoietic origin." (PMID 38550583, 2024). "Our observations correlate with several studies that proved that high soluble MICA levels correlate with poor prognosis in cancer patients." (PMID 36991390, 2023). "Ratios of membrane-bound MICA versus sMICA levels have been shown to influence the outcome in cancer patients." (PMID 38035108, 2023). "The related NKG2D ligands contain major histocompatibility complex (MHC) class I associated chains A and B (MICA, MICB) as well as unique long 16 (UL16) binding protein (ULBP) families, which are expressed on human cancer cells." (PMID 36765808, 2023). "Meanwhile, gemcitabine upregulated MICA expression and attenuated soluble MICA secretion, which in turn enhanced the cytotoxicity of NK cells against cancer cells." (PMID 37253929, 2023). "In cancer, reduced MICA expression diminishes the recognition of NK cells via the NKG2D activating receptor, thereby avoiding the antitumoral immune response." (PMID 38146340, 2023). "MICA plays a crucial role in the host’s innate immune response to several disease settings, including cancer." (PMID 38146340, 2023). "Cancer vaccines targeting MHC class I chain-related protein A/B (MICA/MICB) stress molecules that activate synergistic attacks by T cells and NK cells have demonstrated efficacy and safety in mice and rhesus macaques." (PMID 36797782, 2023). "Many experimental results have demonstrated the presence of soluble NKG2D ligands in the serum of patients with various types of cancer, including MM, in which soluble MICA has been correlated with a progression of the disease." (PMID 37298418, 2023). "Meanwhile, the aberrant expression of MICA in normal tissues and cancer tissues was also evaluated using TIMER 2.0 program by analysing RNA sequence data from TCGA data." (PMID 37784183, 2023). "Our review focuses on MICA-related ceRNA networks, which are proven powerful tools for deciphering cancer mechanisms and predicting therapeutic responses at the system level." (PMID 37784183, 2023). "In HCT116 colon cancer cells and several other cancer cell lines, propionate induces the cell surface expression of immune stimulatory ligands MICA/B and results in NKG2D-mediated cancer cell killing." (PMID 37546420, 2023). "It would be interesting to perform in vitro studies using these miRNAs to analyze their effect on MICA expression, especially in cancer, as MICA plays a crucial role in immune surveillance against this disease." (PMID 38146340, 2023). "The MICA-NKG2D axis is well characterized in the context of cancer, where engagement of MICA on tumor cells by NKG2D unleash NK cell cytotoxicity." (PMID 36466922, 2022). "In cancer, commonly upregulated ligands include MICA and MICB (MHC-class I polypeptide-related sequence A and B), the UL16-binding proteins (ULBPs) and the adhesion molecules PVR (poliovirus receptor, also known as CD155) and Nectin-2." (PMID 35242135, 2022). "Loss of miR-153 resulted in the shedding of MICA, a natural ligand for the NK surface activation molecule NKG2D, from the surface of cancer cell." (PMID 36248881, 2022). "NK cells recognize malignant cells through the recognition of NKG2L, referred to as MHC I ligand UL16 binding protein 1 (ULBP1-6) and MHC class I-related chain A and B (MICA/B) expressed in cancer cells." (PMID 36189271, 2022). "In particular, the activity of membrane-bound MHC class I polypeptide-related sequence A (MICA) (mMICA), which is expressed on the surface of cancer cells, in turn activates cytolytic responses of NK cells against epithelial tumor cells." (PMID 35443621, 2022).
cancer (continued). "This exosome-mediated immunosuppressive phenotype has also been observed in prostate cancer cells where cancer cell-derived exosomes containing MICA/B, ULBP1, or ULBP2 led to the downregulation of NKG2D receptor expression on effector populations." (PMID 35565467, 2022). "A number of cytokines and growth factors, such as TGF-β, IL-10, IFN-γ and EGF function as regulators of MICA expression in different types of cancer cells." (PMID 35967396, 2022). "The induction of hyperploidy in various cancer cell lines by cytochalasin D, a microfilament polymerization inhibitor, resulted in a subsequent upregulation of MICA and an increased NK cell cytotoxic response." (PMID 35565467, 2022). "The MHC -I chain-related polypeptide A/B (MICA/B), expressed in many human cancers, serves as ligands to activate the NKG2D receptor on the NK cells and T cells." (PMID 36159990, 2022). "Then, we used interleukin-2 (IL-2)-treated NK cells from cancer patients and healthy individuals as effectors to target tumors in the absence and presence of anti-MICA/B monoclonal antibodies (mAbs)." (PMID 33440654, 2021). "MICA has been reported to be shed from advanced cancer cells to evade NKG2D-mediated immune detection and elimination." (PMID 34077462, 2021). "MICA is a ligand that is expressed in many cancer cells and can bind NKG2D receptor on NK or T cells." (PMID 34502191, 2021). "For example, MICA has been overexpressed, fused with antibodies and cytokines in cancer therapeutic studies." (PMID 34077462, 2021). "Cancer cells from various solid tumor types were discovered to upregulate MICA/B and ULPB1–3, whereas they downregulated the KIR2D ligands HLA-ABC and HLA-G, suggesting a higher sensitivity to NK cell-mediated cytotoxicity." (PMID 33572396, 2021). "On the other hand, other irradiated cancer cell lines demonstrated to be more resistant to NK cell cytotoxicity by the downregulation of MICA/B, ULPB 1-3, or the upregulation of HLA-ABC." (PMID 33572396, 2021). "We further identified that the activation of MMPs related to MICA/B expression on the surface of cancer cells." (PMID 34502191, 2021). "In the elimination phase of cancer immunoediting, MICA binds to activating receptors on NK cells, leading to the release of pro-inflammatory and immunomodulatory cytokines." (PMID 32683508, 2021). "For example, we found the non-cancer cell line, LO2, which was the most resistant to NK cell cytotoxicity, expressed the highest level of NKG2D ligand, MICA, and also a high level of ULPs when compared with the cancer cell lines." (PMID 34325694, 2021). "A previous clinical study showed that because soluble MICA, which is shed on the surface of cancer cells, occurs at a high level in the serum of patients of various cancers, it is indicative of poor patient survival." (PMID 34502191, 2021). "The handle of the screwdriver is the engineered allogenous off-the-shelf NK cell, while the MICA fusion proteins are the bits targeting different “screws” on cancer cells." (PMID 34077462, 2021). "In that study, a monoclonal antibody was selected that masks MICA and MICB α3 domain, the site of proteolytic shedding by metzincins, namely ADAMs, preventing loss of cell surface MICA and MICB by human cancer cells." (PMID 32283827, 2020). "On the contrary to MICA expressed on cancer cells (also known as membrane MICA), soluble MICA (sMICA) is an unfavorable factor for anti-cancer immunity." (PMID 32222150, 2020). "Since high levels of both forms of soluble MICA and MICB (sMICA/B) have been found in various cancers, the release of MIC proteins is thought to be one cause for cancer immune escape." (PMID 32153595, 2020). "URB597 significantly reduced the soluble MICA level in culture medium and increased the MICA level on the surface of cancer cells." (PMID 32968163, 2020).
cancer (continued). "NK cells kill cancer cells after binding to them through interaction between NK receptors, such as the activating receptor NKGD2, and cancer cell ligands, such as MICA/B and ULBPs, which are HLA-related molecules." (PMID 32526891, 2020). "MICA is one of the necessary negative regulators in cancer immunology, and both MICA and its corresponding receptor are highly expressed in carcinomas and inflammatory lesions." (PMID 32528529, 2020). "Nonetheless, this study demonstrated that soluble MICA only inhibited chNKG2D T cell cytotoxicity at a concentration of 15 μg/ml, significantly higher than levels detected in cancer patient sera (0·2–10 ng/ml)." (PMID 32544282, 2020). "Increases major histocompatibility complex (MHC) class I chain-related protein A (MICA) expression and sensitizes cancer cells to γδ T-cell-mediated killing." (PMID 33312959, 2020). "The selection of an allele for MICA in the population, which is resistant both to viral MICA-binding proteins as well as proteolytic cleavage by host cell metalloproteases upregulated in cancers, may highlight another example of human evolution to bypass cancer and virus-mediated immune evasion." (PMID 33352921, 2020). "Cellular miRNAs such as miR-20a, miR-93 and miR-106b which bind to the 3′ UTRs of MICA/B transcripts are upregulated in many human cancers, and are responsible for the downregulation in MICA and MICB protein." (PMID 33352921, 2020). "Increased HB-EGF level in supernatants and decreased MICA level on cancer cells surface activated the EGFR pathway and induces immune escape, respectively." (PMID 32637415, 2020). "Therapeutic strategies targeting human MICA molecules, for example, by employing MICA-specific antibodies in cancer immunotherapy, are increasingly getting into the focus of current translational research." (PMID 32582150, 2020). "In our human NK and cancer cell co-culture system, we demonstrated that MICA-ICs formed with an α3 domain specific anti-MICA antibody can activate NKG2D and reverse sMICA-mediated NK cell suppression in a Fc-dependent fashion." (PMID 31387641, 2019). "Given the mounting evidence of shed MICA/B in immune suppression, MICA/B is currently being investigated as a potential target for cancer immunotherapy." (PMID 31387641, 2019). "MICA has high cell-surface expression in cancers of the digestive system and have been found to be correlated with increased survival." (PMID 30704450, 2019). "In summary, our results provide new insights on approaches to enhance NKG2D agonism in the presence of soluble MICA in cancer." (PMID 31387641, 2019). "The main site of the proteolytic shedding of MICA/B on the surface of cancer cells is the α3 domain, while the other two α1 and α2 domains bind to the NKG2D receptor." (PMID 31396523, 2019). "Due to the high prevalence of soluble MIC proteins in multiple cancers, targeting the α3 domain serves as an attractive approach to enhance NKG2D signaling in cancers with elevated soluble MICA levels." (PMID 31387641, 2019). "Further studies using cancer cell lines that endogenously express and shed MICA will likely provide more insights for the proposed mechanism of action for α3 domain specific MICA antibodies." (PMID 31387641, 2019). "NKG2D recognizes NKG2D ligands such as ULBP1-6 and MICA/B that are upregulated in many types of cancer cells." (PMID 31071196, 2019). "In particular, IFN-γ increased expression of miR-520b able to inhibit MICA transcript levels in different types of cancer cell lines." (PMID 29662484, 2018). "Infusions of activated NK cells to treat cancer are generally considered safe, and can scavenge soluble MICA in the serum of cancer patients, thereby restoring NKG2D-mediated immune surveillance." (PMID 30254634, 2018). "Soluble form of MICA (sMICA), which is released from cancer cells in order to escape from immune system, is an antagonist of MICA/NKG2D pathway." (PMID 30214375, 2018).
cancer (continued). "In this study we have optimized two methods, ELISA and LFIA, for the detection in exosomes of MICA, a protein released from cancer cells that can affect immune recognition mediated by the activating receptor NKG2D." (PMID 29720199, 2018). "We subsequently proved that pharmacological restoration of membrane-bound MICA in HCC cells boosted natural killer cell-mediated anti-cancer effects, confirming that a MICA sheddase, a disintegrin and metalloproteinase 10 (ADAM10), is a therapeutic target." (PMID 29721164, 2018). "Several studies have suggested that MICA/B levels predict clinical outcomes in patients with cancer; however, this remains contentious." (PMID 29221214, 2017). "Studies of cytokine-induced killer cell (CIK) therapy have reported that cancer patients with high MICA expression experienced a significantly greater survival benefit from CIK treatment." (PMID 29221214, 2017). "CD4+ NKG2D+ T cells with regulatory function were found in both MICA+ cancer patients 18 and juvenile‐onset systemic lupus patients." (PMID 28224733, 2017). "Experimental studies suggest that increased sMICA or MICA was an indicator of poor prognosis in cancer diseases." (PMID 27306684, 2016). "In actuality, the addition of a MICA sheddase inhibitor reinforced the evoked mMICA expression and NK cell cytotoxicity as observed in various cancer cells." (PMID 27910927, 2016). "MICA is highly expressed on cancer cells and can activate antitumor effects from natural killer cells and CD8+ T cells." (PMID 26730743, 2016). "MICA and HLA-E have key functions in the immune responses against cancer, infection and allogeneic solid organ transplant." (PMID 27907087, 2016). "Soluble forms of MICA/B are increased in sera of cancer patients and are postulated to impair antitumor immune response by down regulating expression of NKG2D immunoreceptors." (PMID 27034760, 2016). "Significantly increased serum levels of soluble MICA were found to correlate with poor clinical outcome in patients suffering from various types of cancer." (PMID 26909862, 2016). "Most adherent cell types tested expressed moderate to high levels of MICA, including two primary adherent non-cancer cell types growing as monolayers (fibroblasts and normal human astrocytes)." (PMID 28154561, 2016). "A range of human cell lines of different (mainly cancer-derived) origins which were cultured adherently or in suspension were screened by flow cytometry for MICA surface expression." (PMID 28154561, 2016). "The importance of MICA/NKG2D engagement in the control of cancer has been demonstrated by several studies showing that increased soluble MICA protein in the serum of cancer patients leads to downregulation of NKG2D on NK cells and correlates to poor prognosis." (PMID 27148255, 2016). "We found that increased cell–cell contact reduced MICA expression on cancer cell lines and that signaling through the FAK/Src axis plays a key role in this." (PMID 28154561, 2016). "In the present study, we were interested to analyze the effects of HSF1 activation (Hsp90 inhibitor NVP-AUY922) and inhibition (NZ28, HSF1 knockdown) in different human cancer cells on the NK cell ligands MICA/B and its consequences on NK cell-mediated lysis." (PMID 25854583, 2015). "MICA is highly expressed on viral-infected cells or cancer cells, and acts as ligand for NKG2D to activate antitumor effects of Natural killer (NK) cells and CD8+ T cells." (PMID 23024757, 2012). "Since sMICA was shown to inhibit the antitumor effects of NK cells and CD8+ T cells by reduction of their affinity to binding to target cells, the effect of MICA in cancer cells would be modulated by the expression of MMPs." (PMID 23024757, 2012). "Cancer cells are known to secrete the stress molecules MICA and MICB that activate cytotoxicity by lymphocytes and NK cells through their NKG2D receptor as a mechanism of immunological defense." (PMID 21477352, 2011).
cancer (continued). "Therefore, this study establishes the proof of concept of a next-generation anti-MICA/B antibody for cancer immunotherapy through an Fc optimization that enhances the antibody's ability to elicit NK cell-driven immunity." (PMID 41999749, 2026). "Combining the induction of MICA (pro-inflammatory effect) in cancer cells with the specific inhibition of EHHADH and FAO (anti-inflammatory effect) in macrophages may offer a beneficial therapeutic approach for HCC." (PMID 40723248, 2025). "However, NKG2D ligands, ULBP3 and MICA/B, showed similar expression levels in cancer and normal cells." (PMID 41050660, 2025). "Combining the induction of MICA (pro-inflammatory effect) in cancer cells with the specific inhibition of FAO (anti-inflammatory effect) in macrophages may offer a beneficial therapeutic approach for HCC." (PMID 40723248, 2025). "Two anti-cancer cytokines MICA and IL-2 are consistently increased with combinational treatment." (PMID 40145650, 2025). "Additionally, resveratrol enhances the expression of MHC Class I Polypeptide-Related Sequence A (MICA) and MHC Class I Polypeptide-Related Sequence B (MICB) in cancer cells, making them more susceptible to NK cell-mediated lysis." (PMID 39335671, 2024). "In this study, we present ICOVIR15KK-MICAMut, an oncolytic adenovirus (OAdv) armed with a transgene encoding a non-cleavable MICA to promote NK-mediated cell-killing capacity and activate the immune response against cancer cells." (PMID 38180524, 2024). "Interestingly, a mutant version of MICA resistant to shedding is described, although its application to cancer therapy remains unexplored." (PMID 38180524, 2024). "Conversely, the shedding of MICA/B on the membrane of cancer cells may yield soluble molecules that bind to and downregulate NKG2D on NK cells and CD8+T cells to impair NKG2D-mediated immune responses." (PMID 36765808, 2023). "Several immune-related MICA/NKG2D pathways may be dysregulated in cancer with aberrant miRNA expressions." (PMID 37784183, 2023). "Thus, we were particularly concerned with the regulation of mediated immune escape in the MICA/NKG2D pathway by ncRNAs as potential therapeutic targets and diagnostic biomarkers of immunity and cancer." (PMID 37784183, 2023). "In addition, hsa-miR-1184 plays a significant role in various types of cancers and its impact on MICA expression should be addressed." (PMID 38146340, 2023). "Any cell or cancer type can express MICA if appropriately stimulated." (PMID 37784183, 2023). "At this point, we explored whether MICA could be acquired from cancer cells in an NKG2D independent manner." (PMID 37298418, 2023). "At the same time, the competitive endogenous RNA (ceRNA) hypothesis holds that circRNAs, lncRNAs, and mRNAs induce an abnormal MICA expression by directly targeting downstream miRNAs to mediate mRNA suppression in cancer." (PMID 37784183, 2023). "Consequently, these differences in binding probability can lead to diverse regulatory effects on MICA expression, particularly in the context of miRNA dysregulation in cancer and inflammatory processes." (PMID 38146340, 2023). "NK cells’ killing capacity is tightly regulated by the interaction with both its activating, such as NKG2D, and inhibitory molecules that have costimulating receptors (such as MHC class I chain-related polypeptide (MICA) A and B) and co-inhibitory receptors expressed on the surface of cancer cells." (PMID 36230808, 2022). "Finally, we treated the ECM-detached cancer cells with vitamin C (a global methylation inhibitor) and observed a reduction in the promoter methylation of NK cell ligands, resulting in MICA/B re-expression." (PMID 35323710, 2022). "It has been overlooked whether the upregulated DNA methylation in ECM-detached cancer cells could repress MICA/B expression." (PMID 35323710, 2022).